FGFR2 (fibroblast growth factor receptor 2)
Diseases named in the same sentence as FGFR2 in open-access papers (continued):
Sharing a sentence is not in itself a finding about the gene and the disease.
intrahepatic cholangiocarcinoma (continued). "Since FGFR2 fusion has been demonstrated to be an independent driving factor for the occurrence of intrahepatic cholangiocarcinomas (ICCs), the impact of other mutations on ICC remains unknown." (PMID 37964396, 2023). "However, patients often develop acquired resistance to these inhibitors through the emergence of secondary kinase-activating mutations, as observed in FGFR2 fusion-driven intrahepatic cholangiocarcinoma." (PMID 35574218, 2022). "FGFR2 fusion mutations are reported in 13–20% of patients with intrahepatic cholangiocarcinoma." (PMID 33935756, 2021). "FGFR2 gatekeeper mutation V564F has been reported in three intrahepatic cholangiocarcinoma (ICC) patients treated with Pemigatinib27." (PMID 36697561, 2022). "A 62-year-old woman with FGFR2-fused intrahepatic cholangiocarcinoma (iCCA) involving the hepatocaval confluence and all three hepatic veins, previously deemed unresectable, underwent partial ALPPS-preserving segment IVb." (PMID 41148465, 2026). "FGFR2 inhibition in patient-derived intrahepatic cholangiocarcinoma (ICC) cell lines containing an overactive FGFR2 mutant decreases HK2, PKM2, and LDHA expression." (PMID 39433211, 2025). "In intrahepatic cholangiocarcinoma (iCCA), FGFR2 fusions are most common, occurring in approximately 10–16% of cases and correlating with distinct clinicopathological features." (PMID 41514604, 2025). "In intrahepatic cholangiocarcinoma, FGFR2 fusions are identified in approximately 10–16% of cases, representing the most frequent and therapeutically relevant FGFR aberration in GI cancers." (PMID 41153346, 2025). "FGFR2 fusions are found across a variety of cancer types including in 10%–15% of primary intrahepatic cholangiocarcinomas (ICCs)." (PMID 40014401, 2025). "For patients with FGFR2-positive intrahepatic cholangiocarcinoma, Futibatinib or Pemigatinib are recommended." (PMID 40909948, 2025). "Single-arm study have already demonstrated the clinical benefits of FGFR inhibitor (Futibatinib) in previously treated patients with FGFR2 fusion or rearrangement-positive intrahepatic cholangiocarcinoma." (PMID 41340108, 2025). "FGFR2 fusions occur in up to 14% of patients with intrahepatic cholangiocarcinoma (iCCA) and have been considered as therapeutic target for FGFR inhibitors (FGFRi)." (PMID 40260297, 2025). "Isocitrate dehydrogenase 1 (IDH1) and fibroblast growth factor receptor 2 (FGFR2), the two druggable genes, are frequently reported as therapeutic target gene abnormalities in intrahepatic cholangiocarcinoma (iCCA)." (PMID 40565050, 2025). "Pemigatinib was the first FGFR inhibitor approved for previously treated FGFR2 fusion-positive intrahepatic cholangiocarcinoma, based on the FIGHT-202 trial, which showed an ORR of 35.5%." (PMID 41153346, 2025). "Genetic alterations including fusions in fibroblast growth factor receptor 2 (FGFR2) are detected in 10–20% of intrahepatic cholangiocarcinoma (iCCA), and FGFR2 inhibitors are effective for the treatment of iCCA." (PMID 38532197, 2024). "Multiple FGFR inhibitors have demonstrated significant activity in pretreated advanced FGFR2 fusion–positive intrahepatic cholangiocarcinoma." (PMID 38895132, 2024). "FGFR2 fusions or rearrangements occur in 13%–20% of patients with intrahepatic cholangiocarcinoma (iCCA)." (PMID 39697545, 2024). "Both infigratinib (BGJ398) and pemigatinib are orally bioavailable FGFR1-3 specific inhibitors that are approved as second-line treatment for patients with advanced intrahepatic cholangiocarcinoma with FGFR2 dysregulation." (PMID 38062117, 2023). "FGFR2 as an actionable target in intrahepatic cholangiocarcinoma (iCCA) has been studied in many clinical trials." (PMID 37370984, 2023). "And, it has been approved in September 2022 for the treatment of adult, previously treated, unresectable, locally advanced or metastatic FGFR2 fusions or rearrangements intrahepatic cholangiocarcinoma patients." (PMID 37750089, 2023).
intrahepatic cholangiocarcinoma (continued). "It has preliminary antitumor activity in patients with unresectable or metastatic FGFR2 fusion-positive intrahepatic cholangiocarcinoma (iCCA)." (PMID 36891628, 2023). "The FGFR2 fusion gene is the most common genetic abnormality found in intrahepatic cholangiocarcinoma, and its detection using liquid biopsy is low." (PMID 37046493, 2023). "FGFR2 as an actionable target in intrahepatic cholangiocarcinoma (iCCA) has been tested in many clinical trials." (PMID 37370984, 2023). "Durable response in heavily pretreated advanced intrahepatic cholangiocarcinoma harboring FGFR2 alterations is possible with an FGFR inhibitor." (PMID 38098111, 2023). "Recently, the US Food and Drug Administration (FDA) has approved infigratinib (BGJ398) and pemigatinib in intrahepatic cholangiocarcinoma with FGFR2 fusions, as well as erdafitinib in advanced urothelial cancer with FGFR2/3 alterations." (PMID 38062117, 2023). "FGFR2 fusions or rearrangements occur in 10-16% of patients with intrahepatic cholangiocarcinoma (iCCA)." (PMID 37954763, 2023). "This study performed a cost-effectiveness analysis on the use of targeted therapy pemigatinib 13.5 mg daily in second-line treatment for Taiwanese patients with intrahepatic cholangiocarcinoma (ICC) harboring FGFR2 fusions/rearrangements." (PMID 37697368, 2023). "FGFR2 was commonly elevated in bile duct cancer, especially the intrahepatic cholangiocarcinoma, and thus it is used as a marker and therapeutic target for it." (PMID 36996081, 2023). "FGFR2 alternations have been almost exclusively isolated to intrahepatic cholangiocarcinoma, and the prevalence of this alteration ranges from 10-15%." (PMID 37954763, 2023). "Futibatinib, an irreversible FGFR1-4 inhibitor, has also demonstrated efficacy among previously treated patients with intrahepatic cholangiocarcinoma (iCCA) with FGFR2 fusions/rearrangements in the FOENIX-CCA2 (NCT02052778) pivotal phase 2 trial." (PMID 37954763, 2023). "Eighty-four percent of the FGFR2 fusions were found in the intrahepatic cholangiocarcinoma, a subtype that made up 37% of OAs and 31% of AYAs." (PMID 36433963, 2022). "Currently, pemigatinib and infigratinib use Foundation One as an FDA-approved companion diagnostics test (CDx) for FGFR2 fusions in intrahepatic cholangiocellular carcinoma." (PMID 36231142, 2022). "FGFR2 aberrations are estimated to be present in approximately 15–20% of cases of intrahepatic cholangiocarcinoma (iCCA), which has led to the development and testing of drugs that target FGFR2." (PMID 36290903, 2022). "Novel agents are being tested in clinical trials; for example, the highly selective FGFR2 inhibitor RLY-4008 in a clinical trial of patients with intrahepatic cholangiocarcinoma (and other advanced solid tumors) and FGFR2 alterations (NCT04526106)." (PMID 36462464, 2022). "The ligand-independent activation of FGFR2 is a known oncogenic event predominantly found in intrahepatic cholangiocarcinoma with a prevalence of around 13%." (PMID 35871236, 2022). "Intrahepatic cholangiocarcinoma (iCCA) has emerged as a promising candidate for precision medicine, especially in the case of activating FGFR2 gene fusions." (PMID 34480077, 2021). "Chromosomal translocations involving fibroblast growth factor receptor 2 (FGFR2) gene at the breakpoints are common genetic lesions in intrahepatic cholangiocarcinoma (ICC) and the resultant fusion protein products have emerged as promising druggable targets." (PMID 33692336, 2021). "Genomic analysis has shown that FGFR2 fusions were identified in 13% ~ 50% of intrahepatic cholangiocarcinoma (iCCA) patients." (PMID 34732230, 2021).
intrahepatic cholangiocarcinoma (continued). "Next-generation sequencing has identified actionable genetic aberrations in intrahepatic cholangiocarcinomas (iCCA), including the fibroblast growth factor receptor 2 (FGFR2) fusions." (PMID 30420614, 2019). "In a recent trial, the FGFR2 inhibitor BGJ398 was found to be effective for intrahepatic cholangiocarcinoma patients with activating FGFR2 fusions; however, resistance developed after a short response period." (PMID 28431544, 2017). "Currently, there have been over 11 fusion partners for FGFR2 identified in intrahepatic cholangiocarcinoma patient samples S1 Table." (PMID 27627808, 2016). "Further clinical validation is ongoing with a phase two study in FGFR2 fusion positive intrahepatic cholangiocarcinoma." (PMID 27627808, 2016). "FGFR2 fusions occur in approximately 10–16% of intrahepatic cholangiocarcinomas." (PMID 41514604, 2025). "Notably, FGFR2 fusions and rearrangements are predominantly observed in intrahepatic cholangiocarcinoma (iCCA) and occur in 10–20% of patients." (PMID 38730642, 2024). "The results of phase 2 study FIGHT-202 and FDA approval of pemigatinib in 2020 as the first FGFR1–3 inhibitor in the treatment of advanced intrahepatic cholangiocarcinoma with FGFR2 fusions or arrangements have led to improvements in the therapeutic strategies of this tumor entity." (PMID 38098111, 2023). "In a patient with Stage IVB intrahepatic cholangiocarcinoma with FGFR2 fusion, typical pemigatinib side effects required treatment, but long‐term survival could be achieved by multidisciplinary management of side effects." (PMID 37415592, 2023). "Notably, all FGFR2 fusions were only detected in patients with intrahepatic cholangiocarcinoma, which was expected." (PMID 37341068, 2023). "Intrahepatic cholangiocarcinoma harbours druggable genetic lesions including FGFR2 gene fusions." (PMID 36635225, 2023). "Some cases like those with FGFR2 alterations could have been intrahepatic cholangiocarcinoma and may have been improperly diagnosed as PDA." (PMID 37404765, 2023). "This is in sharp contrast to what is known for intrahepatic cholangiocarcinomas, that have FGFR2 fusions in 10–16% of cases that may be sensitive to infigratinib and pemigatinib." (PMID 36335173, 2022). "Approved on 30 September 2022 for the treatment of intrahepatic cholangiocarcinoma harboring fibroblast growth factor receptor 2 (FGFR2) gene fusions or other rearrangements, futibatinib (brand name Lytgobi®) is a highly selective irreversible fibroblast growth factor receptor (FGFR1–4) inhibitor." (PMID 36432728, 2022). "Treatment with derazantinib produced an overall RR (ORR) of 20.7%, a disease control rate (DCR) of 82.8%, and a median progression-free survival (PFS) of 5.7 months in patients with advanced, unresectable intrahepatic cholangiocarcinoma and FGFR2 fusions who progressed after chemotherapy." (PMID 32962091, 2020). "FGFR2 fusions and ERRFI mutations may represent novel targets in sporadic intrahepatic cholangiocarcinoma and trials should be characterized in larger cohorts of patients with these aberrations." (PMID 24550739, 2014). "Increasing evidence highlights that fibroblast growth factor receptor 2 (FGFR2) fusion/rearrangement shows important therapeutic value for patients with intrahepatic cholangiocarcinoma (ICC)." (PMID 38986528, 2024). "FGFR inhibitors (FGFRi) benefit patients with FGFR2-fusion positive intrahepatic cholangiocarcinoma (ICC) but depth and duration of response is often limited." (PMID 38714664, 2024).
intrahepatic cholangiocarcinoma (continued). "Genomic alterations that activate Fibroblast Growth Factor Receptor 2 (FGFR2) are common in intrahepatic cholangiocarcinoma (ICC) and confer sensitivity to FGFR inhibition." (PMID 38714664, 2024). "It is estimated that 10%–30% of all solid tumors are dependent on the FGFR signaling, with 6%–15% of intrahepatic cholangiocarcinoma (ICC) harboring FGFR2 fusions and arrangements, and 20% of urothelial cancers driven by FGFR3-activating mutations or fusions." (PMID 38602417, 2024). "Fibrosis growth factor receptor 2 (FGFR2) (also in neuron projection morphogenesis, GO:0048812) and its partner driver genes are frequently found in intrahepatic cholangiocarcinoma (ICC)." (PMID 33819263, 2021). "Fibroblast growth factor receptor 2 (FGFR2) was demonstrated to correlate to the progression and prognosis of intrahepatic cholangiocarcinoma (ICC) by numerous evidences." (PMID 30160357, 2018). "Fibroblast growth factor receptor 2 (FGFR2) rearrangements represent one of the most actionable molecular alterations in biliary tract cancer, particularly in intrahepatic cholangiocarcinoma (iCCA)." (PMID 41682001, 2026). "One such agent is pemigatinib, a selective fibroblast growth factor receptor 2 (FGFR2) inhibitor, approved for patients with FGFR2 gene fusions or rearrangements, a genomic alteration observed in a subset of intrahepatic cholangiocarcinoma cases." (PMID 41008657, 2025). "However, patients with intrahepatic cholangiocarcinoma harbor frequent genetic alterations such as isocitrate dehydrogenase (IDH)-1 (20.6–29.1%) and -2 (2.5–4.4%) mutations and fibroblast growth factor receptor 2 (FGFR2) fusions (10–15%), which can be treated with IDH1/2 or FGFR2 inhibitors." (PMID 39660136, 2024). "Gene fusions or rearrangements of FGFR2 are the most common FGFR gene alteration events, and these are found almost exclusively in intrahepatic cholangiocarcinoma to facilitate its progress." (PMID 37750089, 2023). "Most common FGFR alterations for bladder cancer, intrahepatic cholangiocarcinoma, and glioma were FGFR3 SVs (1051/7739, 13.6%), FGFR2 REs (618/6641, 9.3%), and FGFR1 SVs (239/11 550, 2.1%), respectively." (PMID 36462464, 2022). "In contrast, FGFR2-TACC2 fusion without amplification has only been reported in a case of apocrine breast cancer, despite the fact that FGFR2 fusions with various partners, including FGFR2-TACC3, are relatively common in intrahepatic cholangiocarcinoma." (PMID 33853673, 2021). "In this regard, FGFR2–AHCYL, FGFR2–BICC1, FGFR2–PPHLN1, and FGFR2–TACC3 fusions have been frequently described in patients with intrahepatic cholangiocarcinoma, although over 100 different FGFR2 partners have been reported in this disease." (PMID 32962091, 2020). "The FGFR2 F276C VUS was identified as a result of targeted sequencing of a tumor from a 57-year-old male with advanced, multifocal, intrahepatic cholangiocarcinoma." (PMID 30761385, 2017). "Integrated analysis of sporadic intrahepatic cholangiocarcinoma (SIC) genomic and transcriptomic data led to the discovery of FGFR2 fusion products in three of six assessed patients." (PMID 24550739, 2014). "Moreover, for intrahepatic cholangiocarcinoma (ICC), which belong to a type of primary carcinoma of the liver, with FGFR2 gene fusion, sorafenib has a preferable clinical treatment effect." (PMID 33935756, 2021). "Ten patients with intrahepatic cholangiocarcinoma and FGFR2 alterations were treated with an FGFR inhibitor (derazantinib or pemigatinib), with the latter now being approved by EMA in pretreated patients harboring FGFR2 fusions, and five patients received pembrolizumab." (PMID 34436668, 2022). "The FGFR2 fusion necessitates the involvement of the downstream effector Mek1/2, indicating the potential clinical efficacy of dual blockade targeting FGFR2 and MEK1/2 in patients with intrahepatic cholangiocarcinoma (ICC)." (PMID 38831455, 2024).
endometrial cancer (89 papers, 2010 to 2026). Primary or metastatic malignant neoplasm involving the endometrium (mucous membrane that lines the endometrial cavity). "Aberrant FGFR2 signaling has been linked to tumorigenesis in several cancers, including breast, gastric, and endometrial cancers, through the activation of downstream pathways such as MAPK, PI3K/AKT, and STAT signaling cascades." (PMID 39063983, 2024). "In endometrial cancer, the presence of activating mutations in fibroblast growth factor receptor 2 (FGFR2) and disruptions in the mTOR pathway have been identified as potential therapeutic targets." (PMID 38584599, 2024). "FGFR2 mutations have been reported in 10% to 12% of endometrial cancers and are associated with shorter disease-free and overall survival durations, suggesting another therapeutic opportunity." (PMID 37980453, 2023). "The fibroblast growth factor receptor 2 (FGFR2) gene is frequently mutated in endometrial cancer (EC), but the functional implications of FGFR2 mutations in cancer development remain largely unexplored." (PMID 37759450, 2023). "Mutations in the receptor tyrosine kinase gene fibroblast growth factor receptor 2 (FGFR2) occur at a high frequency in endometrial cancer (EC) and have been linked to advanced and recurrent disease." (PMID 37165578, 2023). "Endometrial cancer (EC) exhibits genetic heterogeneity, with mutations in multiple signaling pathway genes, including the FGFR2 signaling pathway, occurring in over 10% of patients." (PMID 37759450, 2023). "This study showed that AP24534 inhibited the migration and invasion of FGFR2‐mutated endometrial cancer cells and had antiendometrial cancer effects." (PMID 36525280, 2023). "FGFR2 missense mutation also occurs in endometrial cancer, diffuse gastric cancer and triple-negative breast cancer." (PMID 35157610, 2022). "The 3 tamoxifen-associated EMPs were not distinctive with respect to their spectrum of definitive endometrial cancer driver mutations, which included FGFR2, PIK3CA, and FBXW7." (PMID 35798968, 2022). "Isoforms of PDGFR and FGFR are expressed in endometrial tumors, with FGFR2 mutations occurring in ~13% of endometrial cancer cases." (PMID 34358108, 2021). "As background for the drug repurposing study described here, we made the novel observation that AZD4547 is active against FGFR2-mutated endometrial cancers." (PMID 34790577, 2021). "To date, the most clinically advanced FGFR TKIs in FGFR targeted treatment is dovitinib (TKI258), which is now being tested in endometrial cancer patients with FGFR2 mutation (NCT01379534)." (PMID 33193890, 2020). "Somatic mutations of the fibroblast growth factor receptor 2 (FGFR2) tyrosine kinase gene were observed in 12% of endometrial cancer cases." (PMID 32570721, 2020). "In endometrial cancer cell lines harboring activating FGFR2 mutations, inhibition of FGFR kinase activity inhibited cell cycle progression, cell survival, and colony formation." (PMID 33193890, 2020). "Pre-clinical cancer models with genetic aberrations in the FGFR pathway, including FGFR2-mutated endometrial cancer, are particularly sensitive to FP-1039 mediated tumor inhibition." (PMID 33193890, 2020). "FGFR2 is thought to be a potential therapeutic molecular target for patients with FGFR2 activation-associated endometrial cancer." (PMID 33193890, 2020).